APOE (apolipoprotein E)
Diseases named in the same sentence as APOE in open-access papers (continued):
Sharing a sentence is not in itself a finding about the gene and the disease.
atherosclerosis (continued). "ApoE and its alleles have a pivotal role not only in healthy individuals but also in pathological states like atherosclerosis, further emphasizing its critical impact in various cardiovascular and metabolic conditions leading to IDFUs." (PMID 38066772, 2023). "A recent study has shown that moxonidine, an agonist for α2 and imidazoline 1 (I1) receptors, inhibits atherosclerosis in apolipoprotein E-deficient (ApoE−/−) mice, possibly via inhibiting inflammation and promoting oxidized LDL uptake and clearance." (PMID 37685939, 2023). "We used Apolipoprotein E-deficient (ApoE−/−) mice as an atherosclerosis model and induced AAA development by the implementation of Angiotensin II-releasing osmotic minipumps." (PMID 37894941, 2023). "On the other hand, deficiency in the PGRN level had worsened atherosclerosis in apolipoprotein E (ApoE) KO mice." (PMID 36658641, 2023). "We observed that by feeding a Western diet to the apolipoprotein E mutant (ApoE−/−), a transgenic mouse model of atherosclerosis, we can reproduce the progressive greying and hair loss observed in men accompanied with wounding of skin." (PMID 38203654, 2023). "Exogenous IL-6 in the apolipoprotein E-deficient (ApoE−/−) model of atherosclerosis increased the formation of atherosclerotic lesions, while the IL-6 receptor antibody downregulated inflammation and reduced atherosclerotic lesion sizes." (PMID 37049512, 2023). "ApoE deficiency is associated with decreased catabolism of atherogenic lipoproteins, favoring hypercholesterolemia and atherosclerosis development." (PMID 37529351, 2023). "The knockout of tissue inhibitor of metalloproteinase 3 (Trim3) in atherosclerosis-prone apolipoprotein E (ApoE)-deficient mice leads to cardiac dysfunction and worsens cardiac remodeling after myocardial infraction." (PMID 36982607, 2023). "Recently, DNA methyltransferase 3b (DNMT3b) was implicated in atherosclerosis progression, as its inhibition was found to ameliorate the plaque content, regulatory T cell (Treg) populations, and inflammation in apolipoprotein E (ApoE) knockout mice." (PMID 38255639, 2023). "Hypercholesterolemic apolipoprotein E deficient (ApoE−/−) mice are routinely used to investigate progressive atherosclerosis because they reveal plaques in the brachiocephalic trunk (BT) with features that represent those in vulnerable human plaques." (PMID 37980508, 2023). "Deficiency of the ADCYAP1 gene encoding pituitary adenylate cyclase-activating peptide (PACAP) aggravates atherosclerosis in ApoE deficient (ApoE−/−) mice." (PMID 37980508, 2023). "In the present study, we investigated the role of DSBs in atherosclerosis development using Ku80-deficient apolipoprotein E-knockout (ApoE−/−) mice." (PMID 37777633, 2023). "One of these showed that S. mansoni-infected, ApoE-deficient mice had 50% less atherosclerosis in the aortic arch and brachiocephalic artery than uninfected mice." (PMID 36827239, 2023). "Several in- vivo experiments have shown that the Ilex kudingcha extract reduces atherosclerosis in apoE-deficient mice by decreasing cholesterol buildup in macrophages." (PMID 37664830, 2023). "Knockdown of ICAM-1 in apolipoprotein E (ApoE−/−)-deficient mice led to reduced vascular lesion size and has been implicated to exert a more important function in the progression of atherosclerosis." (PMID 37830604, 2023). "For instance, Gpr18 and RvD2 were shown to be upregulated in human coronary arteries in presence of atherosclerotic lesions; and the treatment of ApoE-deficient hyperlipidemic mice with the Gpr18 antagonist O-1918 was shown to reduce atherosclerosis." (PMID 37645248, 2023). "To explore the role of CD163 in the process of VC, we crossed atherosclerosis-prone apolipoprotein E–deficient (ApoE–/–) mice with CD163–/– mice (ApoE–/–CD163–/–) (both on a C57BL/6J background) and compared the features of atherosclerosis with ApoE–/– mice." (PMID 36719758, 2023).
atherosclerosis (continued). "Orally administered LPS has been shown to reduce atherosclerosis plaque deposition in the aorta, improve glucose tolerance, and decrease low-density lipoprotein (LDL) in ApoE-deficient atherosclerosis mice." (PMID 37762690, 2023). "The liposomal drug binds to integrin α4β1 receptors on monocytes and has been used to locate plaques in the aortas of ApoE−/− mice, which are known to be susceptible to atherosclerosis." (PMID 37229223, 2023). "Others reported that impaired elastin structure of the vessel wall was associated with the progression of atherosclerosis in ApoE−/− C1039G+/− crossbred mice compared to ApoE−/− mice." (PMID 37560112, 2023). "Animal blood samples for an atherosclerosis diagnostic baseline (training set) were prepared using carotid artery ligation of ApoE−/− mice which were administered a high‐fat diet." (PMID 37476064, 2023). "The effect of moxonidine on atherosclerosis was measured by examining aortic arch Sudan IV staining and quantifying the intima-to-media ratio of the left common carotid artery in apolipoprotein E-deficient (ApoE−/−) mice infused with angiotensin II." (PMID 36835270, 2023). "We also examined eating behavior in female ApoE−/− mice since aberrant meal timing has been linked to atherosclerosis." (PMID 37064902, 2023). "We studied ApolipoproteinE-deficient (ApoE−/−) mice that are a well-established model of atherosclerosis." (PMID 37064902, 2023). "The decreasing of IGF-1 in serum is associated with high cardiovascular disease risk, and IGF-1 administration reduces atherosclerosis in mice with apolipoprotein E knockout." (PMID 38157252, 2023). "A functional role in the progression of atherosclerosis was identified in ApoE-deficient mice (a commonly used mouse model for atherosclerosis), where cathelicidin deficiency significantly decreased atherosclerotic lesion size." (PMID 37090695, 2023). "ApoE-deficient mice served as a widely utilized murine model for studying the progression of AD and atherosclerosis." (PMID 37894967, 2023). "ApoE 4 allele can contribute to atherosclerosis, and it will increase the prevalence of cardiovascular and cerebrovascular diseases and significantly promote vascular disease progression in patients with age." (PMID 36910141, 2023). "The apolipoprotein E-deficient (apoE−/−) mouse is a well-established model for studying atherosclerosis." (PMID 38079017, 2023). "Our findings are comparable with previous studies that reported severe hypercholesterolemia and atherosclerosis in apoE-deficient mice, which worsened when fed a high-fat Western-type diet." (PMID 37108120, 2023). "Its protective role against atherosclerosis is significant, with diminished ApoE expression linked to a proatherogenic lipoprotein profile and advanced atherosclerotic disease." (PMID 38066772, 2023). "Atherosclerosis is a complex multifactorial disease and apolipoprotein E (APOE) polymorphism has been associated with cardiovascular events." (PMID 37629219, 2023). "VX‐765 is a specific inhibitor of caspase‐1, which has been found to attenuate the development and progression of atherosclerosis in ApoE‐deficient mice by inhibiting VSMCs pyroptosis." (PMID 37125240, 2023). "Collectively, these results indicate that GSDME deficiency mitigates diet-induced atherosclerosis and inflammation in ApoE−/− mice." (PMID 36807553, 2023). "Exosomes isolated from murine bone marrow-derived macrophages (BMDM) and infused into atherosclerosis-prone ApoE-deficient Western diet-fed mice exhibit an ability to reduce atherosclerotic lesion necrosis and stabilize atheroma." (PMID 37110138, 2023). "APOE ε4 has several biologic roles leading to the development of dementia including affecting inflammation and atherosclerosis, while APOE ε2 is the protective variant for dementia with the protective biologic mechanisms remaining to be elucidated." (PMID 37584418, 2023).
atherosclerosis (continued). "Our previous studies demonstrated that caspase-1 activation in myeloid cells was associated with HIV-associated atherosclerosis in HIV transgenic (Tg26+/−/ApoE−/−) mice and people with HIV." (PMID 37629052, 2023). "A recent study reports that adropin can contribute to anti-atherosclerosis in apolipoprotein E-deficient mouse (ApoE-/-) mice with high fat diet (HFD) by suppressing monocyte-endothelial cell adhesion and smooth muscle cell (SMC) proliferation." (PMID 37903785, 2023). "When the BMDM exosomes were grown under high glucose conditions to replicate a diabetes-type environment, they caused accelerated atherosclerosis when infused into ApoE−/− mice." (PMID 37110138, 2023). "Mast cell activation during the progression of atherosclerosis has been shown to increase plaque size in the brachiocephalic artery of apoE-deficient mice." (PMID 37663654, 2023). "Another study indicated that CRAMP-mtDNA complexes aggravate atherosclerotic lesion formation in ApoE-deficient mice and suggests that LL-37-mtDNA complex acts as a key mediator of atherosclerosis formation." (PMID 37090695, 2023). "We assessed susceptibility to atherosclerosis of global Tβ4 knockout mice using the ApoE-/- hypercholesterolaemia model." (PMID 37724952, 2023). "Lentivirus-mediated overexpression of miR155 in apolipoprotein E deficient mice accelerated atherosclerosis." (PMID 37226245, 2023). "ApoE-null mice are genetically predisposed to atherosclerosis and develop both spontaneous and diet-induced atherosclerotic plaques, enabling comparisons to pathologic atherogenesis observed in humans." (PMID 38054039, 2023). "ApoE-deficient (ApoE−/−) animals are less efficient at removing cholesterol accumulated in blood vessels and are more likely to develop atherosclerosis." (PMID 37998401, 2023). "The role of IL-6 in the atherosclerotic process was demonstrated in apoE-deficient mice, where recombinant IL-6 injections worsened early atherosclerosis." (PMID 37893519, 2023). "Consumption of sesamin (0.5% w/w) reduced the expression of intracellular adhesion molecule 1(ICAM‐1) and intima thickness in atherosclerosis induced by high‐fat diets in apolipoprotein E (apoE)‐deficient mice." (PMID 37457142, 2023). "We have recently found that global deficiency of MC1-R signaling accelerates atherosclerosis in apolipoprotein E knockout mice (Apoe-/-) by increasing arterial monocyte accumulation and by disturbing cholesterol and bile acid metabolism." (PMID 37490042, 2023). "Caprylate inhibits inflammation through the TLR4/NF-κB signaling pathway, thereby improving atherosclerosis in ApoE-deficient mice." (PMID 36769847, 2023). "Surprisingly, CFI-400945 accelerated atherosclerosis in carotid arteries induced by partial carotid ligation in apolipoprotein E deficient (ApoE−/−) mice fed a high-fat diet." (PMID 36750553, 2023). "Endothelial dysfunction of ApoE−/− rats fed a western diet was reported, which was associated with early-stage atherosclerosis and elevated LDL and triglyceride levels." (PMID 37507899, 2023). "We previously reported a novel metabolically healthy obesity mouse model, in which atherosclerosis is decreased due to proinflammatory microRNA-155 (miR155) deficiency in apolipoprotein E deficient (ApoE–/–) mice but NAFLD development is sustained." (PMID 36776889, 2023). "Vascular dysfunction and atherosclerosis occur early in ApoE-deficient mice, which results in decreased cerebral blood flow and autonomic dysregulation of the cerebrovascular system." (PMID 37396111, 2023). "The increased atherosclerosis in apoE−/− mice expressing CETP was associated with markedly increased SAA immunostaining in aortic root sections." (PMID 37004910, 2023). "The apolipoprotein E-deficient mice have a high cholesterol level and high chances for the development of atherosclerosis, whereas perhexiline decreases systemic cholesterol levels via activation of the KLF14 pathway." (PMID 36837818, 2023).
atherosclerosis (continued). "Some molecules proved to be good targets for inhibiting NLRP3, such as MCC950, with a marked reduction of the atherosclerotic lesions in ApoE-deficient mouse model and future promising perspectives for atherosclerosis." (PMID 37600028, 2023). "Here, we addressed the impact of permanently high S1P levels on atherosclerosis in cholesterol-fed apolipoprotein E-deficient (ApoE−/−) mice over 12 weeks." (PMID 36077004, 2022). "This is an artificial experimental set-up that mimics, to some extent, the up-regulation of LSD1 associated with both human and experimental atherosclerosis, namely atherosclerotic ApoE-/- mice and cultured pro-inflammatory (M1) Mac." (PMID 36552592, 2022). "Introduction of Lp-PLA2 gene into apoE-deficient mice would lead to a reduction in the mean arterial wall thickness and less spontaneous atherosclerosis." (PMID 35433542, 2022). "Crossing full Nr4a3 knock-out mice to apolipoprotein E (Apoe) deficient mice, used to model atherosclerosis, resulted in decreased atherosclerotic lesions." (PMID 35496823, 2022). "To do this, we fed ApoE−/− (apolipoprotein E-deficient) mice, a model of human atherosclerosis, a KD (Kcal%: 1/81/18, carbohydrate/fat/protein) or a control diet (Kcal%: 70/11/18, carbohydrate/fat/protein) for 12 weeks." (PMID 35625895, 2022). "Mitochondrial DNA damage with resultant mitochondrial dysfunction has been associated with the degree of atherosclerosis in early human atherosclerotic specimens and apoE−/− mice with reduced LDL absorption from blood due to lacking apolipoprotein E." (PMID 35534453, 2022). "ApoE-deficient (ApoE–/–) mice have been widely used in preclinical atherosclerosis studies because of the propensity to spontaneously develop atherosclerotic lesions with features similar to those seen in humans." (PMID 35669479, 2022). "More importantly, we reported that LAP+ Tregs induced by nasal oxidized low-density lipoprotein or thymic stromal lymphopoietin attenuated atherosclerosis in apolipoprotein E-deficient (ApoE−/−) mice." (PMID 36405994, 2022). "It has been observed that polymorphisms of the ApoE gene, the protagonist of the expression of this lipoprotein, are correlated with a greater progress of atherosclerosis." (PMID 35741740, 2022). "In the present study, RIPK1S25D/S25D mice containing an S > D mutation in the kinase domain of RIPK1 were crossbred with ApoE−/− mice to investigate the role of RIPK1 kinase activity in experimental atherosclerosis." (PMID 35625752, 2022). "The role of MyD88 and its association with TLRs in the development of atherosclerosis have been studied in ApoE–/–mice." (PMID 35845572, 2022). "Diabetes-associated atherosclerosis (AS) was established in apolipoprotein E knockout (ApoE−/−) mice using high-fat diet and streptozotocin." (PMID 35692570, 2022). "Overall, loss of ITGB3, which encodes integrin β3, exacerbates atherosclerosis in high-fat diet-fed ApoE (−/−) mice." (PMID 36180828, 2022). "The most commonly used models of atherosclerosis are mice deficient in apolipoprotein (ApoE −/−), whose susceptibility to the development of dyslipidemia is increased and subsequently promotes the formation of atherosclerotic plaques." (PMID 36613797, 2022). "Allicin supplementation significantly decreased serum TMAO in ʟ-carnitine-fed C57BL/6 J mice, reduced aortic lesions, and altered the fecal microbiota in carnitine-induced, atherosclerosis-prone, apolipoprotein E-deficient (ApoE−/−) mice." (PMID 35087050, 2022). "On the other hand, leptin receptor-deficient db/db;ApoE–/– have demonstrated accelerated atherosclerosis accompanying hyperglycemia, obesity, hyperinsulinemia and dyslipidemia vs. age-matched ApoE–/– mice." (PMID 36505365, 2022). "Beyond this MHCII-restricted effect, endothelial TRAF6-deficiency protects from atherosclerosis in female ApoE-deficient mice by inhibiting NF-κB-dependent proinflammatory gene expression and monocyte adhesion to EC." (PMID 35252400, 2022).
atherosclerosis (continued). "To investigate the effects of macrophage-specific Tm6sf2 deficiency on atherosclerosis, we obtained myeloid-specific Tm6sf2-deficient mice on ApoE−/− background by crossbreeding with mice expressing the LysM Cre transgene." (PMID 36139452, 2022). "Contrastingly, myeloid cell-specific TRAF6-deficiency caused exacerbated atherosclerosis with larger plaques containing more necrotic areas in both in male and female ApoE-deficient mice." (PMID 35252400, 2022). "In atherosclerosis-prone apolipoprotein E-deficient (ApoE-/-) mice, these NPs localised around the aortas, demonstrating the selective mode of delivery." (PMID 35631521, 2022). "The role of endothelial P2Y2-R in atherosclerosis was further studied in endothelial-specific P2Y2-R-deficient mice on an apoE-KO genetic background that were maintained on a standard chow diet for 25 weeks." (PMID 35682562, 2022). "In one study, overexpression of eNOS in ApoE−/− mice was associated with reduced lesion size whilst another study found eNOS overexpression increased atherosclerosis." (PMID 36497101, 2022). "Manganese superoxide dismutase (Mn-SOD) deficiency can accelerate mtDNA damage and enhance atherosclerosis phenotype in apoE−/− mice." (PMID 35534453, 2022). "Conversely, AnxA2 deficiency suppressed atherogenic integrin α5 signaling induced by oscillary shear stress in a partial carotid ligation model of atherosclerosis in ApoE deficient mice." (PMID 36313572, 2022). "The coronary arteries of female ApoE KO mice fed a Western diet to induce atherosclerosis show a higher susceptibility to NO-dependent endothelial dysfunction." (PMID 35883426, 2022). "The surgical technique induced a low and disturbed flow in the left common carotid artery that caused endothelial dysfunction and rapid atherosclerosis development after two weeks in apoE-KO mice fed a high-fat diet." (PMID 35682562, 2022). "The goal of this study was to investigate the efficacy of hydroxyurea in high-fat diet-fed ApoE-/- mice against atherosclerosis and examine the possible mechanism underlying treatment outcomes." (PMID 36451858, 2022). "In the present study, we aimed to investigate the role of PAD4 on the development of atherosclerosis and disease progression using high-fat diet-fed ApoE–/– mice with bone marrow-restricted PAD4 deficiency." (PMID 36465436, 2022). "Although higher CRF seems to be a protective factor against atherosclerosis in the general population, no studies have investigated this potential effect in subjects with increased genetic risk of atherosclerosis, such as APOE e4e4 carriers." (PMID 36357490, 2022). "ApoE polymorphism, especially ε4 allele (E4/E4 or E4/E3 phenotype), is connected to susceptibility to Alzheimer’s disease and atherosclerosis." (PMID 36297390, 2022). "The apolipoprotein E-deficient (Apo E−/−) mouse model is frequently used in atherosclerosis research." (PMID 35892680, 2022). "Based on our findings and the discussion and analysis, we concluded that ApoE deficiency induced atherosclerosis is partly mediated by the increased iron in aortic tissues in mice." (PMID 35669479, 2022). "SR-B1 KO mice display distinctively large HDL enriched in apolipoprotein E (ApoE) and UC and an increased incidence of pathologies in critical physiological systems, including high atherosclerosis susceptibility." (PMID 36187480, 2022). "Researchers reported that, in apoE-deficient mice, the loss of Akt1 leaded to severe atherosclerosis and Akt3 deficiency in macrophages promoted foam cell formation and atherosclerosis." (PMID 35151267, 2022). "To determine the essential in vivo role of macrophage (M)-Jak2 in atherosclerosis, we generate atherosclerosis-prone ApoE-null mice deficient in M-Jak2." (PMID 35169231, 2022).